TNNT3 (troponin T3, fast skeletal type)
Description:
Troponin T is the tropomyosin-binding subunit of troponin, the thin filament regulatory complex which confers calcium-sensitivity to striated muscle actomyosin ATPase activity.
Synonyms: TnTf; AMCD2B; DA2B; FSSV; DKFZp779M2348; DA2B2; beta-TnTF
Tractability: Small molecule: a drug acting on it is in phase 2 or 3 trials.
Gene: Protein-coding gene on chromosome 11 (1,919,456 to 1,938,711, forward strand). Ensembl gene ENSG00000130595.
Pathways (Reactome):
Muscle contraction: Striated Muscle Contraction
Gene Ontology:
Molecular function: actin binding; calcium-dependent protein binding; tropomyosin binding; troponin C binding; troponin I binding
Biological process: positive regulation of calcium-dependent ATPase activity; regulation of ATP-dependent activity; regulation of striated muscle contraction; skeletal muscle contraction; sarcomere organization; regulation of muscle contraction; striated muscle contraction
Cellular component: troponin complex; cytosol
Genetic constraint (gnomAD): Loss-of-function variants: 36 observed, 54.88 expected, observed/expected ratio (o/e) 0.66, 90% interval 0.5 to 0.87. The upper end of that interval is the gene's LOEUF score, 0.87, which puts it in group 3 of 6, group 1 being the genes least tolerant of losing a copy. Missense variants: 291 observed, 341.85 expected, observed/expected ratio (o/e) 0.85, 90% interval 0.77 to 0.94. Synonymous variants: 120 observed, 114.07 expected, observed/expected ratio (o/e) 1.05, 90% interval 0.91 to 1.22.
Gene-disease validity (ClinGen):
ClinGen rates the evidence that TNNT3 causes each of these diseases.
nemaline myopathy (autosomal recessive): Limited. Nemaline myopathy (NM) encompasses a large spectrum of myopathies characterized by hypotonia, weakness and depressed or absent deep tendon reflexes, with pathologic evidence of nemaline bodies (rods) on muscle biopsy.
Homologues: Orthologues: chimpanzee TNNT3 (99% identical), dog TNNT3 (93% identical), guinea pig TNNT3 (93% identical), pig TNNT3 (92% identical), macaque TNNT3 (85% identical), mouse Tnnt3 (85% identical), rat Tnnt3 (78% identical), rabbit TNNT3 (71% identical), tropical clawed frog tnnt3 (71% identical), zebrafish tnnt3b (65% identical), zebrafish tnnt3a (60% identical), Caenorhabditis elegans tnt-3 (41% identical), and 1 more. Paralogues in human: TNNT2 (62% identical), TNNT1 (62% identical).
Diseases named in the same sentence as TNNT3 in open-access papers:
TNNT3 is named in the same sentence as 35 diseases in open-access papers, as found by Europe PMC text mining. Sharing a sentence is not in itself a finding about the gene and the disease. The quoted sentences say what the papers report.
distal arthrogryposis (7 papers, 2015 to 2024). A muscle tissue disease characterized by congenital joint contractures of hand and feet. "The TNNT3 gene is associated with distal arthrogryposis type 2B2, which is characterized by congenital contractures of the distal limb joints and facial dysmorphism." (PMID 39062310, 2024). "Abnormal expression of TNNT3 mutations has been reported to cause congenital myopathy (e.g., nemaline myopathy and distal arthrogryposis)." (PMID 35692882, 2022). "TNNC2 has been implicated in a novel congenital myopathy, TNNI2 and TNNT3 in distal arthrogryposis (DA), and TNNT1 and TNNT3 in nemaline myopathy (NEM)." (PMID 34502093, 2021). "Dominant mutations in TNNT3 cause distal arthrogryposis (DA) disorders in humans, and depletion of tnnt3a in zebrafish via morpholinos blocks normal myofibrillogenesis." (PMID 25840430, 2015). "The TNNT3 gene encodes the fast skeletal troponin T protein (troponin T3) with an association of distal arthrogryposis type 2B2 with autosomal dominant inheritance, which is characterized by congenital contractures of the distal limb joints and facial dysmorphism." (PMID 39062310, 2024). "Moreover, the same TNNT3 variant has been described in a family with distal arthrogryposis, leading to a far milder phenotype." (PMID 32779773, 2020). "TNNT3 is associated with nemaline myopathy and distal arthrogryposis." (PMID 33231562, 2020). "Previous studies have suggested that human mutations in TNNT3, TNNI2, and TPM2 increase the contractility of fast-twitch muscle fibers and cause distal arthrogryposis (DAs) disease." (PMID 26630129, 2015).
nemaline myopathy (7 papers, 2020 to 2024). "Patients with DA with mutations of the TNNT3 gene that alter Ca2+ sensitivity may have a similar mechanism of pathogenesis, and TNNT3 mutations may lead concomitantly to DA and nemaline myopathy of fast twitch fibers." (PMID 34733179, 2021). "Also there are nemaline myopathy (NEM) and atrial septal defect associated with TNNT3 mutation." (PMID 36386347, 2022).
congenital myopathy (5 papers, 2018 to 2025). "Our findings refine and expand the TNNT3 genotype–phenotype spectrum, suggesting that recessive TNNT3‐related congenital myopathy should be considered a discrete entity caused by biallelic loss‐of‐function variants." (PMID 41473596, 2025). "Through different biochemical approaches, we assessed that recessive TNNT3 variants severely impact protein expression, supporting a distinctive loss of function mechanism in the recessive TNNT3‐related congenital myopathy." (PMID 41473596, 2025). "Recessive TNNT3 variants have emerged to cause a congenital myopathy characterized by progressive severe weakness, hypotonia, hypotonic facies, contractures, laxity, scoliosis, and need for respiratory support." (PMID 41473596, 2025). "While dominant deleterious TNNT3 variants are a well‐known cause of DA, the association of biallelic deleterious changes and congenital myopathy is very recent, with only two cases reported so far." (PMID 41473596, 2025). "As such, this is the first patient reported to harbor compound heterozygous variants in TNNT3, and the p.(Tyr13∗) is the first stop gain variant identified in TNNT3‐related congenital myopathy." (PMID 41473596, 2025). "Recently, homozygous splicing variants in TNNT3 have been reported in two subjects with a distinctive congenital myopathy, only partially overlapping DA2B2." (PMID 41473596, 2025). "Our findings expand the TNNT3 genotype and phenotype spectrum, suggesting that variants resulting in a severe loss of protein function underlie the recessive TNNT3‐related congenital myopathy." (PMID 41473596, 2025). "The recessive TNNT3 variants were found to significantly impact protein levels, supporting a distinctive loss of function mechanism underlying the emerging TNNT3‐related congenital myopathy." (PMID 41473596, 2025). "Although only a very limited number of patients harboring biallelic deleterious variants in TNNT3 have been reported so far, the emerging core clinical phenotype suggests that this congenital myopathy should be considered a discrete entity, with only partial overlap with DA2B2." (PMID 41473596, 2025). "Indeed, deleterious TNNT3 variants may cause dominant DA2B2 but also an emerging recessive congenital myopathy." (PMID 41473596, 2025). "In this study, we identified two novel subjects presenting with myopathic conditions placed at the different ends of the TNNT3 spectrum, featuring dominant DA and recessive congenital myopathy." (PMID 41473596, 2025). "In particular, the presence of DA, facial and limb weakness, hypotonia with decreased reflexes, and respiratory involvement appear to be distinctive of TNNT3‐related congenital myopathy in comparison to DA2B2." (PMID 41473596, 2025). "The report of additional cases will play a crucial role in expanding the phenotypic spectrum of TNNT3‐related congenital myopathy and better delineate the phenotypic continuum with DA2B2." (PMID 41473596, 2025). "Accordingly, TNNT3 is likely to be critical to the disease progression of various types of congenital myopathy." (PMID 35692882, 2022). "Substitutions affecting Arg63 may be recurrent in either DA2B2‐ or TNNT3‐related congenital myopathy." (PMID 41473596, 2025).
distal arthrogryposis type 2B (4 papers, 2020 to 2025). "Another woman with Sheldon Hall syndrome terminated the pregnancy due to a pathogenic variant in the TNNT3 gene (case 29)." (PMID 40098141, 2025). "Heterozygous TNNT3 gene variants are known to cause distal arthrogryposis type 2B." (PMID 32779773, 2020). "A novel small deletion, c.47_49del (p.E18del), in TNNT3 was identified in the proband and his family members and was responsible for Sheldon Hall syndrome (SHS)." (PMID 34217350, 2021).
arthrogryposis (3 papers, 2018 to 2022). A rare, non-progressive congenital disorder characterized by multiple joint contractures which are present at birth. "Distal arthrogryposis is a cause of syndromic TEV that is characterized by variations in genes that encode for components of the muscle contractile complex (MYH3, TPM2, TNNT3, TNNI2, and MYH8), resulting in muscle contractures." (PMID 30134936, 2018). "However, in the Angus cattle, although there were genes involved in inflammatory disease (OXT) and microcystic adenoma (SHISAL2B), the main function of DEGs was enriched in arthrogryposis (TNNT3 and TNNI2) and myopathy and myasthenic syndrome (MSTN, MYH2, and SLN)." (PMID 35495650, 2022). "Whereas the majority of described cases with TNNT3 gene variants are children or adults with or without congenital distal arthrogryposis, there has not been described any case in literature with absent fetal movements leading to the clinical diagnosis of fetal akinesia." (PMID 32779773, 2020).
breast carcinoma (2 papers, 2021 to 2026). "In addition, TNNT3 is a risk factor for breast cancer 39, while its role in melanoma is unclear." (PMID 33758620, 2021).
cardiomyopathies (2 papers, 2020 to 2024). "In humans, a variety of cardiomyopathies are associated with mutations in all three cardiac troponin subunits (TNNT1, TNNT2, and TNNT3)." (PMID 33329019, 2020).
Hypertension (2 papers, 2024 to 2025). The presence of chronic increased pressure in the systemic arterial system. "For the hypertension and atrial fibrillation pairing, signals implicating shared causal variants were seen on chromosomes 4, 7, 11, and 17, in the genes FGF5, HOXA13, in the region spanning LSP1 to TNNT3 and that spanning CYTH1 to USP36 respectively." (PMID 40538118, 2025).
muscular dystrophy (2 papers, 2014 to 2022). Muscular dystrophy (MD) refers to a group of more than 30 genetic diseases characterized by progressive weakness and degeneration of the skeletal muscles that control movement. "Three downregulated DESIs were identified for TNNT3, which is involved in encoding fast skeletal muscle fibers, and whose dysfunction contributes to the development of muscular dystrophy symptoms." (PMID 35480309, 2022). "The strong and muscle-specific staining of CA3, MYL3, and TNNT3 in healthy tissue indicates that detection of increased levels of these targets in blood samples of muscular dystrophy patients originates from the muscle, as these targets are not expressed in other tissues." (PMID 24920607, 2014).
atherosclerosis (1 paper, 2021). A disease characterized by the build-up of fatty material and calcium deposition in the arterial wall resulting in partial or complete occlusion of the arterial lumen. "Statin use was removed because of its high p-value, and the TNNT3 gene was dropped because it is expressed mainly in skeletal muscle tissue and has little to do with atherosclerosis." (PMID 33936038, 2021).
Burkitt lymphoma (1 paper, 2021). A rare form of malignant mature B-cell non-Hodgkin lymphoma. "For Family 3 (Burkitt’s lymphoma), TNNT3, SIRPB1, TRMT1, ITGB4, and DCHS1 were the top-five ranked genes." (PMID 34624066, 2021).
muscle disorders (1 paper, 2022). "Mutations in TNNT3 will cause various muscle disorders, mainly covering distal arthrogryposis (DA)." (PMID 36386347, 2022).
myopia (1 paper, 2024). "Because the retina is a neural tissue, the expression of numerous genes linked to cardiac muscle (MYBPC3, ACTC1, MYL3, MYH7, MYH7B) or to skeletal muscle (MYL1, SMYD1, TNNI2, MYH1B, ACTA1, TNNT3) presents a conundrum for explaining a mechanism for myopia progression." (PMID 39028695, 2024).
Myotonia (1 paper, 2020). An involuntary and painless delay in the relaxation of skeletal muscle following contraction or electrical stimulation. "A previous study showed that 2-fold upregulation of MBNL1 protein by transduction of a recombinant adeno-associated viral vector reversed missplicing of Clcn1, Ldb3, Serca1, and Tnnt3, resulting in a significant reduction in myotonia in a DM1 mouse model." (PMID 32054946, 2020).
Respiratory insufficiency (1 paper, 2014). "Interestingly, patients with respiratory insufficiency have lower levels of TNNT3, MDH2, and ETFA than the ones without, suggesting that patient sub-groups within the DMD cohort could be identified." (PMID 24920607, 2014).
sarcopenia (1 paper, 2014). Progressive decline in muscle mass due to aging which results in decreased functional capacity of muscles. "Decline in human muscle mass and strength (sarcopenia) is a hallmark of the aging process; whether methylation changes in genes such as LMNA, TNNT3, ELN and HDAC4 are a cause or consequence of this process merits investigation." (PMID 24112369, 2014).
Sepsis (1 paper, 2022). Sepsis is defined as life-threatening organ dysfunction caused by a dysregulated host response to infection. "Based on degree centrality, 27 hub genes were selected, in which six genes (MMP9, CD44, EGR1, ACTN2, TNNT3, and PTGS2) were selected on the basis of a multi-network variable selection approach and validated in a well-established sepsis mice model." (PMID 35205254, 2022).
skeletal myopathies (1 paper, 2023). "Mutations in the 3 TnT isoform genes (i.e., TNNT1, TNNT2, and TNNT3) have been found in cardiac and skeletal myopathies, suggesting that TnT plays a key role in striated muscle growth and function." (PMID 37186966, 2023).
myopathies (7 papers, 2021 to 2025). "Two distinct variants were reported in previous patients with recessive TNNT3‐related myopathy, the c.481‐1G>A and c.681+1G>A variants." (PMID 41473596, 2025). "TNNT3 is recognized as a novel effective biomarker for diagnosing RYR1 mutation-associated myopathies." (PMID 35692882, 2022). "MYH1 (AUC: 0.856) achieved the maximum diagnostic value in RYR1 mutation-associated myopathies samples, and the diagnostic values of other genes included the following: TNNT3 (AUC: 0.840), MYLPF (AUC: 0.786), and ATP2A1 (AUC: 0.765)." (PMID 35692882, 2022). "In addition, TNNT3 was significantly reduced in skeletal muscle of RYR1 mutation-associated myopathies and had a high diagnostic value for RYR1 mutation-associated myopathies (AUC: 0.840)." (PMID 35692882, 2022). "A previous study reported a higher abundance of the TNNT3 gene in myopathy of the pectoralis major in fast-growing broilers." (PMID 37621550, 2023). "The ROC curve analysis showed that MYH1, ATP2A1, TNNT3, and MYLPF showed good diagnostic performance for RYR1 mutation-associated myopathies." (PMID 35692882, 2022). "Genetic and clinical features of patients with recessive TNNT3‐related myopathy." (PMID 41473596, 2025). "Interestingly, all of these genes are associated with genetic (cardio)myopathies in humans (TTN, NEB, MYBPC1, TNNT3 and TPM1) or mice (PDLIM3)." (PMID 37000196, 2023). "Four skeletal muscle tissue-specific genes were identified, including MYH1, TNNT3, MYLPF, and ATP2A1, as the potential biomarkers for diagnosing and treating RYR1 mutation-associated myopathies, which provided insights into the transcriptome-level development mechanism." (PMID 35692882, 2022). "Impacted by their good diagnostic properties in RYR1 mutation-associated myopathies, a hypothesis was proposed that MYH1, ATP2A1, TNNT3, and MYLPF are likely to serve as biomarkers for diagnosing RYR1 mutation-associated myopathies." (PMID 35692882, 2022). "Similarly, case 21DG0001 with a homozygous truncating variant in TNNT3 (NM_006757:c.723-2A>G) presented with severe non-immune hydrops fetalis and neonatal death, which have not been reported to date in TNNT3-related myopathy." (PMID 34645488, 2021).
cancer (2 papers, 2020 to 2024). A tumor composed of atypical neoplastic, often pleomorphic cells that invade other tissues. "Regarding the remaining DEPs, Myh4, Acta1, Tnnt3, Mb, Ttn, Actn2, Myh7, Myl1, Mybpc2, Myl3, and Tnnc2 are associated with several cancers." (PMID 39861068, 2024). "Moreover, TNNT3 and MYBPC1 tend to be correlated with ANT1 in RMS patients (R2 cancer analysis, Davicioni E-TABM-1202 dataset)." (PMID 32728477, 2020).
TNNT3 also shares sentences with these, for which no sentence is quoted: tumor (2 papers); alcoholic cirrhosis (1); atrial fibrillation (1); atrial septal defect (1); dilated cardiomyopathy (1); distal arthrogryposis types 1 (1); fibrosis (1); heart failure (1); hyperlipidemia (1); Insulin resistance (1); melanoma (1); myocarditis (1); Obesity (1); osteosarcoma (1); type 2 diabetes (1).